LIG1 (DNA ligase 1)
Diseases named in the same sentence as LIG1 in open-access papers (continued):
Sharing a sentence is not in itself a finding about the gene and the disease.
bladder cancer (1 paper, 2024). "LIG1 also plays a crucial role in the progression of bladder cancer; higher expression of LIG1 was associated with an increased likelihood of cancer progression." (PMID 39234248, 2024). "In our investigation of the association between LIG1 expression levels and specific genomic features of bladder cancer, we performed somatic mutation and CNV analyses using the TCGA bladder cancer database using the BEST online platform." (PMID 39234248, 2024). "In the meta-survival analysis results, the hazard ratio (HR) was 1.34 for the fixed effects model and 1.51 for the random effects model, further confirming that LIG1 is a significant adverse prognostic factor in bladder cancer." (PMID 39234248, 2024). "The transwell assay yielded similar results, suggesting that LIG1 has a substantial role in the migration ability of bladder cancer cells." (PMID 39234248, 2024). "We also validated the regulatory role of LIG1 in bladder cancer cells, as well as its potential as a biomarker and its therapeutic value through cell function experiments." (PMID 39234248, 2024). "We established lentivirus-mediated LIG1 knockdown in T24 cells and subsequently conducted a range of cellular experiments to examine the influence of LIG1 on bladder cancer cell phenotypes." (PMID 39234248, 2024). "Based on the transcriptomic data from GSE13507 and matched clinical data, we found that LIG1 expression in bladder cancer was higher than that in normal tissues, and patients with high LIG1 expression had shorter survival times." (PMID 39234248, 2024). "Our research demonstrates that LIG1 plays a crucial role in promoting bladder cancer malignant progression by heightening proliferation, invasion, EMT, and other key functions, thereby serving as a potential risk biomarker." (PMID 39234248, 2024). "Our research examined the effect of LIG1 on the apoptosis of bladder cancer cells, a vital characteristic of tumour cell activity, using flow cytometry." (PMID 39234248, 2024). "We then established lentivirus-mediated LIG1 knockdown in T24 cells and carried out a series of cellular experiments to explore the effect of LIG1 on bladder cancer cell phenotypes." (PMID 39234248, 2024). "The data indicated that knockdown of LIG1 resulted in a marked increase in the apoptosis rate of bladder cancer cells, in both the early and late stages, as well as in general." (PMID 39234248, 2024). "In the GDSC2 database analysis, high LIG1 expression in bladder cancer showed resistance to drugs such as ERK2440, Staurosporine, Nutlin-3a, Trametinib, ERK6604, Selumetinib, SCH772984, AZD1332, Dasatinib1079, Luminespib1669 and more." (PMID 39234248, 2024). "In the CTRP database, we observed that bladder cancer with high LIG1 expression was resistant to drugs including SGX-523, compound 1B, NSC30930, SJ-172550, Fumonisin B1, TGX-221, CAY10576, Lovastatin, Selumetinib, CID-5951923 and others." (PMID 39234248, 2024). "According to the clinical data from GSE13507, the expression of LIG1 correspondingly increased with higher T stage bladder cancer, indicating enhanced proliferative capacity in bladder cancer with high LIG1 expression." (PMID 39234248, 2024). "We evaluated the influence of LIG1 on the migration ability of bladder cancer cells, a key aspect in tumour formation, using wound healing assays." (PMID 39234248, 2024). "Due to the results of the cell communication and GSVA enrichment analysis, we concluded that LIG1 may induce fibrosis through the proliferation of endothelial cells and epithelial cells; therefore, LIG1 may regulate EMT in bladder cancer." (PMID 39234248, 2024). "For the first time in bladder cancer cells, we analysed the function of the LIG1 gene." (PMID 39234248, 2024).
bladder cancer (continued). "In the drug treatment prediction analysis, the GDSC1 database analysis was used to show that bladder cancer with high LIG1 expression exhibited resistance to a series of drugs including AZD1332, PARP9495, Dyrk1b0191, AZD5438, Bleomycin1392, Bleomycin1378, Refametinib1526, Selumetinib1498 and others." (PMID 39234248, 2024). "Similarly, the expression of LIG1 increased with higher N stage bladder cancer, suggesting that bladder cancer with high LIG1 expression is more prone to lymphatic invasion of the surrounding tissues." (PMID 39234248, 2024). "The Western blotting results showed that knockdown of LIG1 inhibited EMT in bladder cancer cells." (PMID 39234248, 2024). "Furthermore, the CCK-8 assay corroborated these results, suggesting that LIG1 knockdown notably decreased bladder cancer cell proliferation." (PMID 39234248, 2024). "Consequently, we assessed whether LIG1 influenced the cell cycle of bladder cancer cells." (PMID 39234248, 2024).
breast tumors (1 paper, 2010). "In breast tumors and MEFs containing Rb/E2F mutations, DNA ligase 1 and other replication factors' expression are altered." (PMID 20454618, 2010).
cervical squamous cell carcinoma (1 paper, 2023). A squamous cell carcinoma arising from the cervical epithelium. "The results showed that compared with the control group of cervical squamous cell carcinoma SiHa cells, the expression of differential proteins PCNA, ATM, LIG1 and HMGB1 in Ect1/E6E7 cells decreased significantly, while the expression of TDG and OGG1 proteins increased significantly." (PMID 36726132, 2023).
colon adenocarcinoma (1 paper, 2024). "We selected LUAD, BRCA, and colon adenocarcinoma (COAD) in vitro models together with an additional PCa cell line (LNCaP) to test the effect of LIG1 loss in combination with PARPi treatment." (PMID 39718835, 2024).
epilepsy (1 paper, 2018). A brain disorder characterized by episodes of abnormally increased neuronal discharge resulting in transient episodes of sensory or motor neurological dysfunction, or psychic dysfunction. "Lig1 has been documented as an epilepsy-linked gene because Lgi1 mutations result in ADLTE." (PMID 30034322, 2018).
Glucose intolerance (1 paper, 2022). Glucose intolerance (GI) can be defined as dysglycemia that comprises both prediabetes and diabetes. "Lig1 (DNA ligase 1) expression was negatively correlated with body mass, while Fgfr1 expression was positively correlated with both glucose intolerance and body mass." (PMID 36424602, 2022).
invasive carcinoma (1 paper, 2021). A carcinoma that is not confined to the epithelium, and has spread to the surrounding stroma. "Using cBioPortal, a breast-invasive carcinoma dataset was used to analyze LIG1 and LIG3 alterations, including mutations, putative copy-number alterations from GISTIC and mRNA expression z-scores relative to diploid samples (RNA Seq V2 RSEM)." (PMID 34825062, 2021).
Lupus (1 paper, 2022). "We developed and characterized phospho-specific antibodies for DNA ligase 1 (LIG1) pS66 (ARVLGpSEGEEE) and Lupus La protein (SSB) pS366 (KTKFApSDDEHD)." (PMID 35755813, 2022).
malaria (1 paper, 2025). Malaria is a serious and sometimes fatal disease caused by a parasite that commonly infects a certain type of mosquito which feeds on humans. "Here, we found that Lig1 is located primarily in the nucleus in both human and rodent malaria parasites throughout the parasite life cycle." (PMID 41395979, 2025).
myelodysplastic syndrome (1 paper, 2013). A clonal hematopoietic disorder characterized by dysplasia and ineffective hematopoiesis in one or more of the hematopoietic cell lines. "Four of these polymorphisms were located in oxidative damage/DNA repair genes (LIG1, RAD52, MSH3 and GPX3), which may play important roles in the pathobiology of myelodysplastic syndromes." (PMID 23339595, 2013).
neuropathy (1 paper, 2020). A disorder affecting the nervous system that manifests with pain, tingling, numbness, and/or muscle weakness. "In our study we observed decreased expression of Lig1 gene (fold = −3.605), which contribution to the development of neuropathy has been described." (PMID 31979371, 2020).
Pca (1 paper, 2023). "By combining both KEGG analysis and GO term analysis, seven genes (RNASEH2A, RFC2, RFC4, LIG1, POLD1, POLD2, and POLE4) were identified as new biomarker genes upregulated in CRPC compared to localized Pca and associated with DNA replication and DNA repair." (PMID 37950047, 2023). "We identified six DDR-related genes (Ribonuclease H2 Subunit A (RNASEH2A), replication factor C subunit 2 (RFC2), RFC4, DNA Ligase 1 (LIG1), DNA polymerase D1 (POLD1), and DNA polymerase E4 (POLE4)) that were upregulated in CRPC compared with Pca tissues." (PMID 37950047, 2023).
psoriasis (1 paper, 2004). An autoimmune condition characterized by red, well-delineated plaques with silvery scales that are usually on the extensor surfaces and scalp. "Targeted disruption of the Lig-1 gene in mice yields hyperplastic epidermal lesions reminiscent of psoriasis as a result of keratinocyte hyperproliferation, and a comparison of human tissue samples showed a loss of Lig-1 expression in psoriatic skin." (PMID 14735165, 2004). "Since autocrine activation of the EGF receptor is a major contributor to keratinocyte proliferation in psoriasis, these observations point to the possibility that Lig-1 negatively regulates EGF receptor." (PMID 14735165, 2004).
renal cell carcinoma (1 paper, 2003). "In all, 31 renal cell carcinomas (RCCs) were examined for expression of the potential tumour suppressor LRIG1 (formerly Lig-1) and the epidermal growth factor receptor (EGFR)." (PMID 14520461, 2003).
serous carcinoma (1 paper, 2021). "High nuclear LIG1 was significantly associated with serous carcinoma (p < 0.0001), higher FIGO stage at presentation (p < 0.0001), higher tumour grade (p < 0.0001), sub-optimal debulking (p = 0.004) and residual tumour following surgery (p = 0.014) compared to tumours with low LIG1 expression." (PMID 34373746, 2021).
Telangiectasia (1 paper, 2023). Telangiectasias refer to small dilated blood vessels located near the surface of the skin or mucous membranes, measuring between 0.5 and 1 millimeter in diameter. "Notably, the PCNA S228I mutation impairs FEN1 and LIG1 interactions and results in clinical features, including short stature, hearing loss, premature aging, telangiectasia, neurodegeneration, and photosensitivity in humans." (PMID 37205694, 2023).
thyroid cancer (1 paper, 2025).
triple-negative breast carcinoma (1 paper, 2023). An invasive breast carcinoma which is negative for expression of estrogen receptor (ER), progesterone receptor (PR), and human epidermal growth factor receptor 2 (HER2). "In addition, genetic deletion or low expression of LIG1 was found to be associated with selective carboplatin resistance in preclinical models of triple-negative breast cancer (TNBC)." (PMID 38044421, 2023).
urothelial carcinoma (1 paper, 2024). A malignant neoplasm derived from the transitional epithelium of the urinary tract (urinary bladder, ureter, urethra, or renal pelvis). "LIG1 has the potential to be a novel therapeutic target for urothelial carcinomas and could help us to better understand the relationship between smoking, a well known risk factor, and urothelial carcinoma susceptibility." (PMID 39234248, 2024). "In summary, through the combination of machine learning and single-cell sequencing analysis, we have identified a new prognostic gene for urothelial carcinoma, LIG1, which may be related to the proliferation and invasiveness of urothelial carcinoma." (PMID 39234248, 2024). "Finally, the expression of LIG1 in urothelial carcinoma has not been studied." (PMID 39234248, 2024).
cancer (37 papers, 2009 to 2026). A tumor composed of atypical neoplastic, often pleomorphic cells that invade other tissues. "We analyzed pan-cancer TCGA genomic and transcriptomic data and detected LIG1 loss-of-function alterations with concomitant decrease in expression in multiple tumor types." (PMID 39718835, 2024). "LIG1 ligates nascent DNA of the lagging strand, and a mutation in LIG1 causes replication errors, genome instability, and cancer." (PMID 24969172, 2014). "Here we show that LIG1 blockade could be an attractive synthetic lethality strategy in XRCC1 deficient cancer cells." (PMID 34373746, 2021). "We then proceeded to test if LIG1 blockade via L82 monotherapy could be a synthetic lethality strategy in DNA repair deficient cancer cells." (PMID 34373746, 2021). "Intriguingly, mutations that compromise LIG1 activity are also affiliated with cancer." (PMID 30590694, 2019). "Consequently, LIG1 function is intimately linked with proliferative capacity and its upregulated expression has been documented in human cancers." (PMID 30590694, 2019). "Additionally, the present study demonstrates that unfilled gaps left by polβ, wild-type or cancer-associated mutants, are erroneously ligated by LIG1, resulting in a deviation from canonical BER pathway coordination and the formation of aberrant repair intermediates with one nucleotide deletions." (PMID 38366780, 2024). "LIG1, an encoded protein, functions in DNA replication, recombination, and base excision repair process, whose disruption may be associated with varieties of cancers." (PMID 33102601, 2020). "Using a CRISPR/Cas9‐based combined screening approach that integrates RNAi with CRISPRn and CRISPRi, researchers identified DNA ligase I (LIG1) as a novel synthetic lethal target in BRCA1‐mutant cancers." (PMID 41537447, 2026). "Moreover, our findings demonstrated that polβ cancer-associated variants Y265C, E288K and E295K leave the gap repair intermediate unfilled even in the presence of correct nucleotides, which leads to gap ligation by LIG1 and the formation of deletion mutagenesis products." (PMID 38366780, 2024). "The current findings proposed innovative cancer drug discovery targeting class 1 HDACs, highlighting LIG1 and LIG2 as potential inhibitors for cancer treatment, emphasizing their interaction pattern and stability in bounded complexes." (PMID 38675404, 2024). "We validated the SL interaction between LIG1 and PARP in multiple cancer models and in PCa xenografts and provided initial evidence supporting the efficacy of combined LIG1 and PARP pharmacological inhibition." (PMID 39718835, 2024). "We dissect how ribonucleotide challenge and cancer-associated mutations could adversely impact the ability of polβ to efficiently fill the one nucleotide gap repair intermediate which subsequently results in gap ligation by LIG1, leading to the formation of single-nucleotide deletion products." (PMID 38366780, 2024). "As for the explants, MBD4 and LIG1 had higher expression in obese patients compared to lean participants and cancer patients (p < 0.05)." (PMID 36982562, 2023). "As previously reported, LIG1 is highly expressed in various types of cancers for rapid proliferation of cancer cells." (PMID 37950047, 2023). "A small molecule inhibitor of LIG1 (L82) was tested for synthetic lethality application in XRCC1, BRCA2 or ATM deficient cancer cells." (PMID 34373746, 2021). "While elevated expression of LIG1 is frequently observed in cancer cell lines, this has been assumed to reflect the hyperproliferative state of cancer cells since LIG1 expression correlates with proliferation." (PMID 34373746, 2021).
cancer (continued). "Our current work thus provides an important cue to develop a therapeutic strategy for cancers with FEN1, POL δ and LIG1 mutations in which Okazaki fragment joining is strongly suppressed upon treatment with PARP and HDAC inhibitors." (PMID 33872376, 2021). "In previous studies, increased levels of LIG1 have been observed in cancer cells lines compared with normal cells, likely related to increased proliferation." (PMID 34373746, 2021). "For these reasons, we have examined the unequivocal contribution of LIG1 to a specific DNA repair mechanism that operates at dysfunctional telomeres in a human cancer cell line." (PMID 30590694, 2019). "The expression level of LIG1 was found higher in human cancer cells, and the ligase is essential for embryonic development, but some studies have demonstrated that LIG1 is not required for cellular DNA replication and that either LIG3α or LIG4 can substitute for joining Okazaki fragments." (PMID 41346861, 2025). "Given that JMJD1B deficiency increases sensitivity to PARP1 inhibition, our results suggest a potential new mechanism by which synthetic lethality is induced for cancer treatment by coupling JMJD1B gene deficiency (e.g., 5q syndrome) or LIG1 deficiency with PARP inhibitors." (PMID 41280084, 2025). "Consistent with that, we show that CB inhibits the expression of several genes associated with DNA repair pathways—including RAD51 and DNA ligase I (LIG1) and consequently inhibits the heightened DNA repair activity that cancer cells employ to survive and proliferate." (PMID 35610507, 2022). "To evaluate whether LIG1 inhibition is synthetically lethal in XRCC1 deficient cells, we tested L82 in a panel of cancer cell lines." (PMID 34373746, 2021). "LIG1 (which was also found to be a component of the base excision repair pathway in KEGG analysis of MMNK-1 cholangiocytes) and FN1, which are implicated in diseases and cancer, were significantly correlated genes with the increase in 1,2-DCP level in the co-cultured MMNK-1 cells." (PMID 35780190, 2022). "Thus, LIG1 provides scope to understand the fundamental and pervasive connections between DNA replication, repair, cytoskeletal organization and intracellular signalling that are transformative in cancer." (PMID 30590694, 2019). "It has been reported that LIGs (including LIG1, LIG3 and LIG4) play important roles in the occurrence and progression of many cancers." (PMID 34825062, 2021). "This enzyme is co-distributed with BRG1 at highly acetylated promoters of genes such as CDK4, LIG1, or NEIL3, which are responsible for cancer cell growth and the removal of DNA damage." (PMID 31614656, 2019). "Comparison of the mouse skin pRb/p107/p130 signature mapped to human genes with Signature 5 of mucosal HPV-carcinomas revealed a significant overlap of 7 genes: DHFR, E2F1, LIG1, MCM2, PCNA, RFC4, TYMS and USP1." (PMID 19721808, 2009). "Combined treatment with LIG1 and PARP inhibitors selectively reduces cancer cell proliferation." (PMID 39718835, 2024). "The translational corollary of this is that LIG1 may be a valuable target for cancer therapeutics since proliferating rather than normal healthy somatic cells would be more severely afflicted." (PMID 30590694, 2019). "Even though our and others’ previous studies show that FEN1 deficiency/inhibition and PARP1 inhibition synergistically kill cancer cells, our new observations suggest that the efficacy of combined FEN1 inhibition and PARP1 inhibition in killing cancer cells may at least partly depend on LIG1 status." (PMID 41280084, 2025). "However, TYMS, DUT, POLB, LIG1 and FEN1 have been identified by others as PARGi synthetic lethality genes, and these observations support the notion that inhibition of nucleotide biosynthesis and BER can sensitize cancer cells to pharmacological PARG inhibition." (PMID 39015544, 2024).